AMACR (alpha-methylacyl-CoA racemase)
Diseases named in the same sentence as AMACR in open-access papers (continued):
Sharing a sentence is not in itself a finding about the gene and the disease.
tumor (continued). "In the current study, all PRNRP cases exhibited a diffuse and strong expression of PAX8, CK7, and GATA3, whereas the expression of AMACR, CD10, and vimentin was either absent or only weak and focal, and the tumor cells were completely negative for CD117 and CAIX." (PMID 35936734, 2022). "In addition, the tumor cells were negative for PSA (inset), but positive for androgen receptor, v-ets erythroblastosis virus E26 oncogene homolog (ERG), and alpha-methylacyl-CoA racemase (AMACR)." (PMID 33263827, 2020).
cancer (75 papers, 2005 to 2025). A tumor composed of atypical neoplastic, often pleomorphic cells that invade other tissues. "Elevated AMACR levels have been linked to many cancer types, including renal cell carcinoma, gastric cancer, ovarian cancer, and hepatocellular carcinoma." (PMID 37371647, 2023). "Loss of the basal cell population and expression of AMACR are indicators of cancer used in prostate histology and contribute to a cancer diagnosis." (PMID 35472129, 2022). "In order to confirm the genetic mutation of AMACR in many types of cancer and its expression in cancer cells, it is necessary to study the molecular mechanism of AMACR." (PMID 32760737, 2020). "Further studies are required to determine if AMACR splice variants have a distinct catalytic activity and play a role in normal and cancer cells." (PMID 32760737, 2020). "The overexpression of AMACR was shown to be associated with the aggressive behavior of multiple human cancers." (PMID 31164957, 2019). "Xenografts from all patients contained malignant tumors as shown by H&E pathology, α-methylacyl-CoA racemase (AMACR) expression and loss of p63+ basal cells." (PMID 27351281, 2016). "Recently, several lines of evidence have linked the racemase activity of AMACR to alterations in cancer cell behavior." (PMID 25473890, 2014). "AMACR is an important diagnostic marker, which is highly expressed in several cancers." (PMID 39544692, 2024). "In addition, identification of multiple splice variants of AMACR is necessary to confirm the correct association between branched chain fatty acids and cancer." (PMID 32760737, 2020). "However, little is known about the mechanisms underpinning AMACR overexpression that causes metabolic deregulation in cancers." (PMID 25473890, 2014). "Combining our discovery (the protective role of rs2278008 in AMACR), the missense mutation by the minor allele of the sequence variant might disrupt or decrease the enzyme (AMACR) activity, subsequently leading to unfavorable energy supply in the cancer cells." (PMID 24383053, 2013). "For example, AMACR’s variability is influenced by the altered metabolism of cancer cells, including factors such as resource availability, stage of growth, and metastatic potential, all of which restrict its clinical utility." (PMID 41465218, 2025). "First, we evaluated cancerous and normal prostate tissue samples for the presence of cancer markers AMACR and EZH2." (PMID 36769153, 2023). "We found that the cells of early PCCs and corresponding PDOs expressed epithelial and cancer markers (AMACR, TMPRSS2-ERG, and EZH2)." (PMID 36769153, 2023). "The cells from the prostate tissue, PCCs, and PDOs were assessed for the epithelial basal (CK5, p63) and luminal (CK18, AR1) markers, mesenchymal (vimentin) marker, and cancer (AMACR, TMPRSS2-ERG, and histone methyltransferase EZH2) markers by RT-PCR." (PMID 36769153, 2023). "PGCC were found to express cancer-related markers such as α-methylacyl-CoA racemase (AMACR), or telomerase reverse transcriptase (TERT)." (PMID 37444476, 2023). "Transcripts of AMACR, GOLM1, TRPM8 and NKX3-1 genes were overexpressed and were closely associated with cancer aggressiveness, extracapsular extension and vesicular seminal invasion." (PMID 37091783, 2023). "IHC confirmed the presence of an invasive prostatic acinar adenocarcinoma with expression of alpha-methylacyl-CoA racemase (AMACR) in the cancer cells of the original patient sample." (PMID 36643868, 2022). "AMACR (alpha‐methylacyl‐CoA racemase) is an enzyme that is overexpressed in PCa and was therefore used to distinguish areas of cancer in the PCa tissue sections." (PMID 35472129, 2022). "Clusters 5, 6, and 11 expressed luminal epithelial markers, AR, AR-induced genes, and cancer cell markers (ERG and AMACR), supporting their identity as cancer cells." (PMID 36229464, 2022).
cancer (continued). "Three genes, AMACR (ENSG00000242110), PCAT14 ((ENSG00000280623) prostate cancer-associated transcript 14), and LTF (lactotransferrin) are frequently compared in studies of prostate data." (PMID 36360315, 2022). "Our results show that the majority of our cells come from luminal epithelial cells as expected, with high accessibility to cancer markers AMACR and EPCAM." (PMID 34911933, 2021). "Further investigation will be warranted to elucidate how AMACR upregulates butyric acid, made challenging because of the complexity of altered fatty acid metabolism in cancer and the role of native colonic microbiota in fatty acid production and breakdown." (PMID 33755595, 2021). "All of these have been reported to be involved in the growth and survival of cancer cells by inhibiting the expression of AMACR in cancer cells." (PMID 32760737, 2020). "The oncogenic role of AMACR was subsequently described in several other carcinoma types, including their precursors, albeit with variable prognostic implications." (PMID 31904088, 2020). "This was most often due to cancer with poor AMACR staining; while AMACR is a sensitive positive marker of PCa, it is well-documented that some variants of PCa do not exhibit increased expression of AMACR29,30,37,38." (PMID 31061447, 2019). "On the other hand, AMACR is a positive cancer marker that is usually highly overexpressed in PCa as well as HGPIN and IDC-P21,28,29." (PMID 31061447, 2019). "Our results provide evidence that the AMACR promoter can be exploited to drive the cancer-specific expression of reporter genes and potentially even be incorporated into conditionally replicative adenoviruses for oncolytic therapy and other applications." (PMID 30613352, 2018). "From these experiments, we identified a 565 bp minimal AMACR promoter that was cancer-specific and possessed output equal to or greater than the full-length promoter." (PMID 30613352, 2018). "Since its initial discovery in PCa, AMACR overexpression has been documented in a number of other cancers including colon, ovarian and breast." (PMID 30613352, 2018). "In this scenario, CRAd replication can be guided by the cancer-specific AMACR promoter allowing for tissue-specific replication in the PCa leading to cancer cell death." (PMID 30613352, 2018). "On the protein level, expression of AMACR is sometimes detected in benign biopsies from patients with PCa, as well as in normal glands that were in closer proximity to a carcinoma foci." (PMID 26928323, 2016). "In the systematic study of cross-sections, AMACR mRNA was detected in all of the studied areas including histologically benign tissue, but at significantly higher levels in carcinoma areas (p < 0.001)." (PMID 26928323, 2016). "AMACR protein expression was detected in 80 % (28/35) of the areas that contained carcinoma and in 37 % (44/119) of the benign and PIN areas from the same patients." (PMID 26928323, 2016). "We found that in contrast to the carcinoma-free CP specimens where AMACR expression was rare, AMACR mRNA was detectable in all benign, carcinoma and PIN samples obtained from the three studied prostate cross-sections with highest levels in carcinoma samples." (PMID 26928323, 2016). "It is noteworthy that ADAMTS12, AMACR, SLC45A2 and C1QTNF3 are associated with cancers, which are all hallmarked by CIN (aneuploidy)." (PMID 26543751, 2015). "We selected AMACR as a target in this study because of its routine use in cancer diagnostics and the good correlation of expression at the mRNA and protein level." (PMID 25514598, 2015). "For example, TSGs derived from HRPCa-3 expressed a high level of AMACR in both control and castrated mice, whereas AMACR-expressing cancer cells were only observed in TSGs derived from HRPCa-6 maintained in control but not castrated mice." (PMID 23985008, 2013). "AMACR is required to enter into the fatty acid oxidation, resulting in energy production for the cancer cells." (PMID 24383053, 2013).
cancer (continued). "Serial sections were stained with antibodies against AMACR to identify cancer cells and Ki67 to label proliferating cells." (PMID 23985008, 2013). "This study concludes that AMACR immune-reactivity is statistically significantly higher in the sera from cancer case subjects than from the control subjects." (PMID 25586028, 2012). "Because of the cancer specificity and high frequency of AMACR expression, it can be an attractive target for cancer immunotherapy." (PMID 20003233, 2009). "CG12-16 deletions were found in all six histological entities; however, their frequency markedly increased in well- (56%) and moderately (89%) differentiated cancers and correlated with high AMACR expression in these lesions (mean expression score ∼3)." (PMID 19148275, 2009). "Aberrant expression of AMACR was recently reported in Cca; however, little is known about how this gene is abnormally activated in cancer." (PMID 19148275, 2009). "Because it has characteristics of cancer-specific expression and frequent expression in various cancers, AMACR is an attractive target for cancer immunotherapy." (PMID 20003233, 2009). "Despite many studies on AMACR expression in human cancer, few studies are available describing the role of AMACR expression in HCC." (PMID 18577240, 2008). "We thus performed immune-morphological studies with cancer-related markers such as α-methylacyl-CoA racemase (AMACR), prostate-specific membrane antigen (PSMA), and telomerase reverse transcriptase (TERT) to understand if the giant cells we found are PGCC or other urinary cells." (PMID 37444476, 2023). "Early PCCs and PDOs derived from the tissues of PCa patients expressed prostate basal and luminal epithelial markers, as well as cancer markers AMACR, TMPRSS2-ERG, and EZH2, the latter being a promising candidate to mark the transition from the indolent to aggressive PCa." (PMID 36769153, 2023). "PCaT samples and derived PDOs expressed cancer markers AMACR, EZH2 and TMPRSS2-ERG." (PMID 36769153, 2023). "The mechanism of how AMACR mediates CRC differentiation (or any other type of differentiated cancer), however, remained unknown until now." (PMID 33755595, 2021). "Indeed, lowering the expression of AMACR in cancer cells via si-RNA has been shown to reduce the growth of cancer cells." (PMID 32760737, 2020). "Taken together, these findings suggest that AMACR has an important function in cancer cells." (PMID 33154941, 2020). "Several AMACR inhibitors have been developed as potential cancer treatments." (PMID 33154941, 2020). "The AMACR promoter can induce cancer-specific expression of a reporter gene." (PMID 32760737, 2020). "However, the pathological relationship between β-oxidation and branched-chain fatty acids in cancer cells with high expression of AMACR is unclear." (PMID 32760737, 2020). "It is thought that the post-transcriptional modification site of AMACR may be important for the function of AMACR expressed in many cancers." (PMID 32760737, 2020). "Increased expression of AMACR also affects the survival of cancer patients (Lee, 2019)." (PMID 32760737, 2020). "AMACR promotes cancer progression through fatty acid β-oxidation." (PMID 33154941, 2020). "Alpha-Methylacyl-CoA racemase (AMACR) is a marker of carcinoma stem cells." (PMID 33154941, 2020). "However, AMACR+ benign luminal cells (n = 508) showed similar AR expression as AMACR+ cancer cells (0.113 vs. 0.112, p = 0.191)." (PMID 29138507, 2017). "However, the expression of AR in AMACR− cancer cells was remarkably stronger than in either AMACR+ cancer cells or AMACR− benign epithelial cells, whereas AMACR+ cancer cells and AMACR+ benign luminal cells showed similar AR expression." (PMID 29138507, 2017). "Levels of AMACR are increased in prostate and other cancers, and it is a drug target." (PMID 26537174, 2016).
cancer (continued). "Moreover, the expression level of AMACR in common carcinomas is known to be mostly regulated by various transcriptional factors, such as C/EBP family members, Sp1, and ZNF202." (PMID 25473890, 2014). "The cancer cells (except LuCaP49) could be distinguished by their expression of any one of the cancer genes AMACR, PCA3, AGR2; their expression levels were variable." (PMID 21605402, 2011). "Because of its cancer-specific and frequent expression, AMACR could be an attractive target for cytotoxic T-lymphocyte (CTL)-based immunotherapy for cancer." (PMID 20003233, 2009). "In addition, the protein levels of AMACR have increased significantly in many types of cancer." (PMID 32760737, 2020). "However, little is known about how AMACR becomes activated in cancer cells." (PMID 19148275, 2009). "In the primary cancer samples, the expression of PCA3, ERG, NPY, and AMACR was significantly upregulated, making them the characteristic genes with the largest expression differences." (PMID 39988626, 2025). "However, the mechanisms of AMACR hyperproduction in cancer are still unknown." (PMID 36769153, 2023). "Thus, AMACR may be an important target for anti-cancer therapeutics." (PMID 33154941, 2020). "Our findings support AMACR as a potential biomarker in GBM patients and a potentially important target for anti-cancer drugs." (PMID 33154941, 2020). "In our study, the AAb panel comprising ERG, AMACR, and HERV-K Gag yielded an AUC of 0.792 for differentiating cancer cases from healthy controls." (PMID 28191285, 2016). "These cancers also had very few other aberrations including the double-deletion at CG3 and 10, in their AMACR promoter CGI." (PMID 19148275, 2009). "AMACR was localised to the cytoplasm of luminal cells of benign epithelium or HG-PIN and to the cytoplasm of carcinoma cells." (PMID 18648369, 2008). "IHC analysis revealed AMACR+ and BCC+ staining, with AMACR positivity in the cancer foci." (PMID 40565112, 2025). "AMACR, while overexpressed in cancer, is not consistently detected in all malignancies and is subject to variability due to metabolic conditions." (PMID 41465218, 2025). "Interestingly, about 50% of PCaT samples and derived organoids expressed another cancer marker, TMPRSS2-ERG, in addition to AMACR and EZH2." (PMID 36769153, 2023). "In contrast, in PCa, TET1 was abundantly expressed exclusively in AMACR-positive cancer cells, whereby not all AMACR-positive cells expressed TET1." (PMID 34844636, 2021). "Future research is needed to determine factors that elevate AMACR expression in some cancer tissues, but not in others." (PMID 31436750, 2020). "To demonstrate this, we detected and automatically classified 83,558 cells in the whole tissue section as stromal, basal epithelial, benign luminal epithelial, or cancer cells, and then measured the expression of CK8, CK18, AMACR and AR in all the cells quantitatively." (PMID 29138507, 2017). "The detected overexpression in cancerous tissues was 682-fold for AMACR mRNA and 11.5-fold for AR mRNA compared to prostates without any evidence of cancer." (PMID 26928323, 2016). "As expected, AMACR staining was strongly positive in the great majority (but not all) carcinoma and PIN lesions." (PMID 26928323, 2016). "While the great majority of normal prostatic glands were AMACR negative, we occasionally observed some weak AMACR staining in morphologically benign glands especially adjacent to carcinoma lesions." (PMID 26928323, 2016). "The second case (initially reported as inflammation) with inflammation and squamous metaplasia, the suspicious large glands showed negative HMWCK staining and strong positivity (3+) for AMACR, hence relabeled as carcinoma." (PMID 21176184, 2010). "It is of interest that the frequency of deletions of all kinds was low in poorly differentiated cancers; 72% of these foci have no lesions in the AMACR promoter CGI." (PMID 19148275, 2009).
cancer (continued). "In contrast, CG12-16 deletions are associated with moderate and well differentiated CCa that express high AMACR but not in poorly differentiated cancers that show negligible AMACR expression." (PMID 19148275, 2009). "Latest literature reports indicate the important role of AMACR gene, however, it is not clear whether it can be considered tissue or cancer specific marker." (PMID 27803125, 2016). "Cancer cells were also positive for K18 and AMACR, and negative for ERG." (PMID 23985008, 2013). "Alternatively, during their evolution, these cancers may acquire a metabolic phenotype that is independent of AMACR overexpression." (PMID 19148275, 2009). "AMACR immunostaining was almost absent to negligible in poorly differentiated carcinomas." (PMID 19148275, 2009). "High expression which is present in a high percentage of HCC, but in only small percentage or rarely in non-HCC tissue, suggests that AMACR may be a target for cancer treatment by using AMACR antibodies or enzyme inhibitors." (PMID 18577240, 2008). "AMACR immunohistochemistry can show dramatic pictures of strongly positive cancer glands infiltrating perfectly negative benign prostatic parenchyma and in these cases its use may turn a diagnosis of atypical glands into a straightforward diagnosis of cancer." (PMID 18781151, 2008). "Compared with the expression in normal crypt, levels of AMACR expression, represented as a score of 0 to 4, were significantly increased in VAs and in well- and moderately differentiated carcinoma but not in normal apex, TAs, and poorly differentiated carcinoma." (PMID 19148275, 2009). "Unlike the better differentiated CCas, most poorly differentiated cancers had a low percentage of deletions at CG12-16 and lacked AMACR expression." (PMID 19148275, 2009).
adenocarcinoma (12 papers, 2008 to 2025). A common cancer characterized by the presence of malignant glandular cells. "Background and Objectives: This study aimed to elucidate the diagnostic role of α-Methylacyl-CoA racemase (AMACR) immunohistochemistry in gastric dysplasia and adenocarcinoma." (PMID 39336516, 2024). "This study aimed to elucidate the diagnostic role of AMACR immunohistochemistry in gastric dysplasia and adenocarcinoma." (PMID 39336516, 2024). "The summary of existing evidence on immunohistochemical markers supplemented with our own data highlighted a differential diagnostic role for AMACR, CK34βE12, CK7, β-Catenin, CD15, and CEA which can be helpful in the routine differential diagnostic workup of adenocarcinomas in the bladder." (PMID 29721106, 2018). "TSPY was strongly expressed in adenocarcinoma cells positive for AMACR." (PMID 24528896, 2014). "Patterns of AMACR expression concurred between adenocarcinoma and NEC components of adenoNEC." (PMID 22782380, 2012). "Next, we investigated the negative rate of AMACR expression in gastric dysplasia and adenocarcinoma, to evaluate the heterogeneity of AMACR expression." (PMID 39336516, 2024). "PIN lesions expressed AMACR and basal cytokeratins, while adenocarcinoma glands expressed AMACR without basal cytokeratins." (PMID 28881646, 2017). "Conversely, approximately half of high-grade dysplasia or adenocarcinoma cases may not exhibit AMACR expression, highlighting the potential variability in the expression patterns between biopsied and resected specimens." (PMID 39336516, 2024). "All ASAP's showing moderate to strong circumferential granular or diffuse positivity with AMACR and a negative staining with HMWCK were relabeled as adenocarcinoma." (PMID 21176184, 2010).